PLEKHA2 (pleckstrin homology domain containing A2)
Description:
Binds specifically to phosphatidylinositol 3,4-diphosphate (PtdIns3,4P2), but not to other phosphoinositides. May recruit other proteins to the plasma membrane (By similarity).
Synonyms: TAPP2
Tractability: Antibody: its Gene Ontology location is reachable by antibodies, with high confidence; UniProt places it where antibodies can reach, with medium confidence. PROTAC: UniProt records ubiquitination sites on it; ubiquitination databases record sites on it; its protein half-life has been measured.
Gene: Protein-coding gene on chromosome 8 (38,901,235 to 38,973,912, forward strand). Ensembl gene ENSG00000169499.
Subcellular location: Cytoplasm; Cell membrane; Nucleus
Subcellular location (Human Protein Atlas): Cytosol; Nuclear bodies; Nucleoplasm
Pathways (Reactome):
Metabolism: Synthesis of PIPs at the plasma membrane
Gene Ontology:
Molecular function: fibronectin binding; laminin binding; phosphatidylinositol-3,4-bisphosphate binding; protein binding; phospholipid binding; PDZ domain binding
Biological process: positive regulation of cell-matrix adhesion
Cellular component: cytoplasm; membrane; protein-containing complex; plasma membrane; nucleus
Genetic constraint (gnomAD): Loss-of-function variants: 27 observed, 46.26 expected, observed/expected ratio (o/e) 0.58, 90% interval 0.43 to 0.81. The upper end of that interval is the gene's LOEUF score, 0.81, which puts it in group 3 of 6, group 1 being the genes least tolerant of losing a copy. Missense variants: 393 observed, 502.06 expected, observed/expected ratio (o/e) 0.78, 90% interval 0.72 to 0.85. Synonymous variants: 178 observed, 182.82 expected, observed/expected ratio (o/e) 0.97, 90% interval 0.86 to 1.1.
Homologues: Orthologues: chimpanzee PLEKHA2 (99% identical), macaque PLEKHA2 (98% identical), rabbit PLEKHA2 (93% identical), pig PLEKHA2 (91% identical), dog PLEKHA2 (91% identical), guinea pig PLEKHA2 (91% identical), mouse Plekha2 (89% identical), rat Plekha2 (79% identical), tropical clawed frog plekha2 (58% identical), zebrafish plekha2 (50% identical). Paralogues in human: PLEKHA1 (44% identical).
Diseases named in the same sentence as PLEKHA2 in open-access papers:
PLEKHA2 is named in the same sentence as 12 diseases in open-access papers, as found by Europe PMC text mining. Sharing a sentence is not in itself a finding about the gene and the disease. The quoted sentences say what the papers report.
breast carcinoma (1 paper, 2015). "Analysis of differential expression levels highlighted CLDND1, PLEKHA2, ACSL3, SLC30A9, MSN, CALM3 and PRKAR1A as potential regulators of breast cancer cell survival since they were affected by PKCδ siRNA in all cell lines." (PMID 26083392, 2015).
juvenile idiopathic arthritis (1 paper, 2020). Juvenile idiopathic arthritis (JIA) is the term used to describe a group of inflammatory articular disorders of unknown cause that begin before the age of 16 and last over 6 weeks. "It is reported that PLEKHA2 is associated with juvenile idiopathic arthritis and rheumatoid arthritis." (PMID 32496000, 2020).
osteoporosis (1 paper, 2020). A condition of reduced bone mass, with decreased cortical thickness and a decrease in the number and size of the trabeculae of cancellous bone (but normal chemical composition), resulting in increased fracture incidence. "Herein, we first found the significant expression of PLEKHA2, PLEKHB1, PNPLA7, SCD, MGST3 and TSNAX in osteoporosis of postmenopausal women, which may be valuable in understanding the pathology mechanism of the disease." (PMID 32496000, 2020).
retinal disease (1 paper, 2012). "Based on putative function and/or involvement in retinal disease, we selected 16 genes – Bach2, Cdr2, Dusp12, Esrrb, Gpsm2, Haus1, Kdm5b, Lman1, Lrp11, Lrrc2, Ncoa2, Plekha2, Ppargc1b, Trim36, Wisp1 and Zdhhc14." (PMID 22511886, 2012).
PLEKHA2 also shares sentences with these, for which no sentence is quoted: cancer (2 papers); depression (1); esophageal squamous cell carcinoma (1); leukemia (1); lymphoma (1); prostate carcinoma (1); rheumatoid arthritis (1); tumor (1).